LPAR1 (lysophosphatidic acid receptor 1)
Diseases named in the same sentence as LPAR1 in open-access papers (continued):
Sharing a sentence is not in itself a finding about the gene and the disease.
tumor (79 papers, 2004 to 2025). "In conclusion, our study delineates the crucial role of MSN in TNBC tumor initiation and chemotherapy resistance, which is closely linked to the signaling cascade initiated by IL-6 binding to LPAR1." (PMID 40696387, 2025). "Expression of LPAR1 in prostate tumours is associated with better overall survival for patients, probably owing to increased anti-tumour immunity." (PMID 38607068, 2024). "One of the richest sources of LPA is platelets, and activation of LPAR subtypes (LPAR1 to LPAR6) has been linked to tumor cell proliferation, migration, cytokine production, and angiogenesis." (PMID 36806315, 2023). "As far as we know, this is the first study to elaborate the potential functions of LPAR1 and its association with tumor-infiltrating immune cells by using integrated bioinformatics analysis." (PMID 32656075, 2020). "We evaluated the association between LPAR1 and tumor-infiltrating immune cells from the mRNA expression data." (PMID 32656075, 2020). "The association between LPAR1 and tumor-infiltrating immune cells were evaluated in the Tumor Immune Estimation Resource site, ssGSEA, and MCPcounter packages in R studio." (PMID 32656075, 2020). "While tumor-promoting activities are more consistently associated with LPAR1–3, which are all coupled to the Gi/Ras/MAPK pathway, LPAR4–6 predominantly show anti-tumor activities." (PMID 31658655, 2019). "The lysophosphatidic acid receptor 1 (LPAR1) is mechanistically implicated in both tumor metastasis and tissue fibrosis." (PMID 29805748, 2018). "In this patient, both expression level and the fraction of mutant allele of LPAR1 was among the highest of the 15 commonly mutated genes, implying a potential driver oncogene function in this tumor." (PMID 24147068, 2013). "Since there is a close association of LPAR1 with the PI3K-Akt signaling pathway, LPAR1 may cooperate with PIK3R5 to exert tumor-suppressing effects, which needs further exploration." (PMID 35884407, 2022). "However, it is very difficult to apply just a ligand-protein LPA clinically, especially if the mutation of LPAR1 and the function of other LPARs in NB tumor cells remain unclear." (PMID 35884407, 2022). "The results of this study support the idea that one function of primary cilia is to limit GBM proliferation, and that loss of tumor cell cilia may lead to the redistribution of LPAR1 to the plasma membrane and lead to cell proliferation as a result of increased LPAR1 signaling." (PMID 30842728, 2019). "The decrease of LPAR1 levels was also reported in public single-cell data from Lee and colleagues, showing a prevalent expression in tumor stroma." (PMID 39980011, 2025). "Song and colleagues showed that the LPAR1 gene was highly expressed in normal colorectal tissue and downregulated in tumor cells after the analyses of more than 2,000 transcriptomes of CRC samples." (PMID 39980011, 2025). "Our study is the first to report LPA-induced IL-10 production by tumor cells and identifies LPAR1-dependent upregulation of DR6 receptors in mediating this effect." (PMID 39187677, 2025). "Other notable receptors include protease-activated receptor 1 (PAR1), which induces tumour invasion and metastasis, and lysophosphatidic acid receptor 1 (LPA1), which plays a role in tumorigenesis and chemoresistance." (PMID 40994571, 2025). "The administration of Debio-0719, a highly specific LPAR1 antagonist, reduced tumor cell migration to the lungs and bones." (PMID 39062979, 2024). "Many studies have shown that overexpression of ENPP2 inhibits the ability of ferroptosis to prevent the development of hypoxia/reoxygenation (H/R) injury (Fang, Shen & Liao, 2023) and can enhance tumor cell spreading, migration, and metastasis through LPAR1." (PMID 39717045, 2024). "LPAR1, a member of the lysophosphatidic acid receptor family, has been reported in previous studies due to its role in tumor cell proliferation, survival, invasion, and metastasis." (PMID 38395755, 2024).
tumor (continued). "Inflammatory signaling pathways were elevated, particularly in high-LPAR6-expressing tumors in all cohorts, and in tumor suppressor pathways apart from DNA repair pathways in high-LPAR1-, LPAR4-, and LPAR6-expressing tumors." (PMID 37372960, 2023). "Enpp2 promotes tumor cell dispersal, migration, and metastasis through LPAR1 and T cell motility through LPAR2." (PMID 37052764, 2023). "Numerous studies have documented a critical role for LPAR1 in enhancing tumor motility and metastasis." (PMID 35769713, 2022). "Taken together, our findings demonstrate the downregulation of LPAR1 in NB cells and the tumor-suppressing effects of the LPA-LPAR1 axis." (PMID 35884407, 2022). "It has been reported that binding of LPA to tumor cells LPAR1 promotes tumor invasion, and the combination of LPA with platelets LPAR5 regulates platelet aggregation." (PMID 35659308, 2022). "LPAR1 was reported to be closely associated with the PI3K-Akt signaling pathway and tumor development, supporting the DEG screening procedures in our study." (PMID 35884407, 2022). "The controversial research results about LPAR1 suggest its different signaling transduction pathways and functions in different types of tumor cells." (PMID 35884407, 2022). "Beyond that study and our analysis based on data from the bone marrow of NB patients, the expression and function of LPAR1 in metastatic NB tumor cells remain to be further explored." (PMID 35884407, 2022). "LPA activates LPAR1, which activates 74 different genes that are important in tumor progression, invasion, and metastasis, for example, vimentin (VIM)." (PMID 35814375, 2022). "Our research verified the decreased expression of LPAR1 in NB cells, and the tumor migration inhibitory effects of LPA on NB cells via LPAR1." (PMID 35884407, 2022). "For lung A549 cancer cells, the LPAR1/Gi/MAP kinase/NF-κB pathway is involved in LPA-induced oncogenesis, and using the LPAR1/3 antagonist Ki16425 to block LPAR1-mediated signaling would significantly reduce tumor volume." (PMID 34209775, 2021). "To compare the mRNA expression levels of LPAR1 in normal and tumor tissues, we used the Oncomine database to determine the LPAR1 expression among multiple cancer types." (PMID 32656075, 2020). "Then, we analyzed the RNA sequencing data downloaded from TCGA and compared the tumor samples between samples with high LPAR1 expression and samples with low LPAR1 expression." (PMID 32656075, 2020). "Lysophosphatidic acid receptor 1 (LPAR1) is a critical gene and it mediates diverse biologic functions in tumor." (PMID 32656075, 2020). "Gene Ontology (GO) analysis, Gene Set Enrichment Analysis (GSEA), and several methods were also utilized to explore the potential function of LPAR1 in tumor progression and immune microenvironment." (PMID 32656075, 2020). "With the LPAR1 upregulated, the M1 macrophages infiltrate into tumor sites and exert an anti-tumor function." (PMID 32656075, 2020). "LPAR1/3/6 mRNA expression was more elevated than non-tumor liver tissue, and LPA6 mRNA expression was highest." (PMID 32284748, 2020). "LPAR1 also downregulates the infiltration of Treg cells, which protect the human body from tumor suppression." (PMID 32656075, 2020). "The level of LPAR1 protein was significantly higher in lymph node metastasis and relapsed more in OSC tissues than in primary tumor lesions, and high levels of LPAR1 protein suggested poor prognosis." (PMID 32284748, 2020). "In vitro biological functions, including invasive, migratory, and proliferative capacities, and in vivo tumor formation were significantly decreased in the LPAR1-silenced ITH cell models." (PMID 31384176, 2019). "The tumor tissues were fixed with formalin, embedded in paraffin, and stained with H&E and IHC to detect LPAR1 expression." (PMID 31384176, 2019). "LPAR1 expression correlated with EMT in tumor area and with the worse prognosis after liver resection." (PMID 31652837, 2019).
tumor (continued). "Compared with the primary tumor lesions, increased LPAR1 staining was observed in the recurrent and lymphatic metastatic lesions from the same patients." (PMID 31384176, 2019). "Biological functions in vitro, including invasion, migration, and proliferation, and tumor formation in vivo were decreased in the LPAR1-silenced cells (all P < 0.05)." (PMID 31384176, 2019). "The H-scores for LPAR1 staining in the lymphatic metastatic and recurrent lesions were noticeably higher than in the primary tumor lesions from the same patients (P = 0.024/0.031)." (PMID 31384176, 2019). "show that the signaling adapter protein N-WASP coordinates recycling of LPAR1 back to the cell surface after internalization, driving efficient matrix remodeling, invasion, and tumor egress." (PMID 31668663, 2019). "The H-scores for LPAR1 staining in the lymphatic metastatic lesions and recurrent lesions were noticeably higher than the primary tumor lesions (159.08 ± 27.23 vs 145.69 ± 29.45, P = 0.024; 165.25 ± 21.49 vs 145.69 ± 29.45, P = 0.031, respectively)." (PMID 31384176, 2019). "In tumor cells, LPAR1, LPAR2, and LPAR3 are the major subtypes, while LPAR5 and LPAR6 are expressed only at very low levels in a subset of patients, if at all." (PMID 30353652, 2019). "Although EOC cells mainly express the LPAR1–3, LPAR6 is the main LPA receptor on TAM and tumor-associated T cells." (PMID 29987226, 2018). "LPAR1–6 mRNA expression was examined in 3 human tumor cell lines of hepatic origin (SKHep1, HepG2, and HuH7)." (PMID 26701886, 2016). "Given that the inhibition of both B7-H3 and LPAR1 could impede CAFs' proliferation and subsequently reduce NSCLC cell proliferation and tumor growth, it would be prudent to explore LPAR1/B7-H3 inhibitory strategies in NSCLC treatment regimens." (PMID 40801642, 2025). "Immunohistochemistry was used to detect LPAR1 expression in tumor tissues." (PMID 40512336, 2025). "In GBM, LPAR1 promotes tumor growth and invasion through altered mitochondrial bioenergetics." (PMID 40018519, 2025). "We observed an abnormal increase in glutamate levels in TC-anlotinib-resistant cell lines during early-stage metabolome sequencing, accompanied by an abnormal decrease in LPAR1 levels, as revealed by transcriptome sequencing, both of which were subsequently confirmed in tumor tissues." (PMID 40512336, 2025). "Analyses of publicly available data on breast cancer have also shown that LPAR1, 4 and 6 gene expression negatively correlate with tumour aggressiveness, while on the contrary, high LPAR2 expression is associated with increased tumour grade and reduced patient survival." (PMID 38607068, 2024). "Our results showed that in the small intestine, RARG (Retinoic Acid Receptor Gamma) show the highest expression, while fibroblasts from tumors predominantly express LPAR1 (Lysophosphatidic Acid Receptor 1), highlighting a possible importance in tumor tissue formation." (PMID 39766077, 2024). "The tumor-suppressing effects of the LPA-LPAR1 axis suggest that LPAR1 might be a potential target for future treatment of NB." (PMID 35884407, 2022). "In contrast, it would seem that LPAR1 mRNA levels could be correlated with high protein levels and it has a functional role in tumor progression." (PMID 33916643, 2021). "Studies show that LPAR1 enhances metastasis and tumor motility." (PMID 34209775, 2021). "In addition, LPAR1 was also positively correlated with tumor-infiltrating immune cells based on the GSE6956 dataset." (PMID 32656075, 2020). "The differential expression of LPAR1 was seen in a set of cancers between tumor and normal tissues." (PMID 32656075, 2020). "However, the LPAR1-correlated functions and mechanisms in tumor immunology and tumor progression remain to be explored." (PMID 32656075, 2020). "The LPAR1 expression was significantly negatively related to tumor purity." (PMID 32656075, 2020).
tumor (continued). "In addition to LPAR1 signaling, CCRK and its substrate, ICK, have been linked to the regulation of ciliogenesis and proliferation of tumor cells." (PMID 30842728, 2019). "Xenograft experiments were performed to test and verify the role of LPAR1 in tumor formation." (PMID 31384176, 2019). "Intriguingly, different LPAR subtypes may have opposing functions in tumor cells, as described, for instance, for the role of LPAR1 and LPAR2 in the LPA‐triggered migration of pancreatic cancer cells." (PMID 30353652, 2019). "Hence, these findings suggest that stromal/host ATX and LPAR1 could be targeted simultaneously to further inhibit tumor progression and metastasis." (PMID 36080255, 2022). "In addition, pharmacological LPAR1 receptor antagonism may significantly reduce tumoral lymphatic vessel density and nodal metastasis in tumor-bearing nude mice, suggesting the key role of LPAR1 in prostate cancer lymphatic metastasis." (PMID 34209775, 2021). "In addition, the H-score for LPAR1 staining in the primary tumor lesions was significantly higher in the patients with a PFS of less than 12 months or OS of less than 36 months (P = 0.017/0.039), indicating that higher levels of the LPAR1 protein were associated with a worse prognosis." (PMID 31384176, 2019). "However, other studies have pointed out also a role of LPAR1 in tumor per se." (PMID 31652837, 2019). "Microglia are affected by lysophosphatidic acid (LPA) secreted by GBM cells, thereby activating them through the lysophosphatidic acid receptor 1 (LPA1), which in turn promote tumor proliferation and migration." (PMID 40075663, 2025). "Low LPAR1 expression affected the proportion of tumor immune infiltrating cells (TIICs) in the tumor microenvironment (TME), which was related to the involvement of LPAR1 in pathways such as CSK and Th1/Th2." (PMID 41462160, 2025). "LPAR1 activation by LPA leads to chemoresistance and radioresistance of tumor cells by upregulating nuclear factor erythroid 2-related factor 2 (Nrf2), multidrug resistance transporters, and anti-oxidant proteins." (PMID 37636389, 2023). "In this study, we showedthat the integrationof the small molecules(<500 Da) of an LPAR1 antagonist, Ki16425, into the lipid bilayerof liposomal vesicles enhanced liposomal uptake by MBC cells in vitroand tumor accumulation in a mouse model of MBC." (PMID 37844135, 2023). "Conversely, knockout of LPAR1 gene or oral LPAR1 antagonist can inhibit lung metastasis, illustrating the significance of LPA-LPAR1 axis in tumor invasion and metastasis." (PMID 35659308, 2022). "LPA binds to at least six G protein-coupled receptors (namely LPAR1-6) to stimulate activation of the ATX-LPA signaling pathway and participates in the regulation of tumor occurrence, progression, and metastasis." (PMID 35769713, 2022). "Our analysis suggested that both LPAR1 and LPAR6 expression were beneficial to NB patients’ survival, possibly involved in the regulation of tumor metastasis mediated by LPA." (PMID 35884407, 2022). "Our results show the decreased expression of LPAR1 in NB cells, demonstrating that LPA can exert tumor migration-inhibitory effects on NB cells via LPAR1." (PMID 35884407, 2022). "With both tumor cells and TAM expressing similar levels of LPAR1 and LPAR2, LPAR3 was predominantly expressed in tumor cells, while LPAR5 and LPAR6 were selective for TAM." (PMID 32397679, 2020). "Hence, high LPAR1 expression may contribute to the migration of immune cells to the tumor tissues." (PMID 32656075, 2020). "In line with this, elevated LPAR1/LPAR3 expression in HCC was evidenced in the microenvironment between the tumor and non-tumor liver (NTL) and LPAR3 expression coincided with cancer stem cell markers expression." (PMID 31652837, 2019). "In summary, trafficking of LPAR1 mediated by N-WASP is crucial for the coupling of LPAR1 signaling with RhoA-mediated actomyosin contraction and force generation during tumor cell chemotaxis, invasion, and dissemination." (PMID 31668663, 2019).
tumor (continued). "On the other hand, the rest of the LPARs (LPAR1, LPAR3 and LPAR5) presumably are involved in the tumor growth via modulating its microenvironment." (PMID 31652837, 2019). "In tissues from the same patients, the levels of the LPAR1 protein were noticeably higher in the lymphatic metastatic and recurrent OSC tissues than in the primary tumor lesions." (PMID 31384176, 2019). "Human HCC were characterized by significantly elevated LPAR1/LPAR3 expression in the microenvironment between the tumor and non-tumor liver (NTL), a finding mirrored in human SKHep1 cells." (PMID 26701886, 2016). "LPA in ascites apparently targets tumor cells and TAMs via specific receptors, since LPAR1 and LPAR2 are expressed at similar levels by both cell types, LPAR3 is selective for tumor cells, LPAR5 and LPAR6 for TAMs." (PMID 27215396, 2016). "KEGG and PPI analyses revealed that GNG11, LPAR1, and AGTR1, as key factors in cancer biological processes, are significantly downregulated in CC, suggesting their potential role as tumor suppressor genes, which is of profound importance in unveiling the pathogenesis of CC." (PMID 41244534, 2025). "This evidence supports the hypothesis that the down- and upregulation of LPAR1 and LPAR3, respectively, are correlated with the tumor transformation of the pancreatic duct cells." (PMID 39062979, 2024). "Interestingly, utilizing the miR-21 inhibitor or silencing LPAR1 or ZEB-1 completely prevented the LPA-induced cell migration and also prevented invasion and tumor cell bone colonization entirely in vitro and in vivo, respectively." (PMID 35814375, 2022). "Furthermore, Ki16425 is one of the most investigated agents targeting both LPAR1 and LPAR3, and its anti-tumor effects were validated in several cancer cells." (PMID 34209775, 2021). "To begin to determine what might be the role of CCN1 expression by CAFs, we used CAF single-cell expression data to identify a group of six genes (PDGFRA, COL1A1, DCN, TAGLN, COL6A3, and LPAR1) that strongly correlated with CCN1 expression, yet were minimally expressed in other tumor cell types." (PMID 38363129, 2024). "In a seminal murine tumor study examining the overexpression of ATX and LPAR1, LPAR2, and LPAR3 in a mouse mammary tumor virus model, the LPAR2-overexpressing model had the highest tumorgenicity rate at 52.8%, followed by ATX at 50.0%, LPAR3 at 42.3%, and LPAR1 at 32.0%." (PMID 37372960, 2023). "Interestingly, the rest of the LPARs (LPAR1, LPAR3–5) are decreased in the HCC liver as compared to adjacent normal tissue, suggesting that LPAR2 and LPAR6 are probably expressed in the tumor whereas the rest LPARs are expressed in the surrounding microenvironment." (PMID 31652837, 2019). "It is interesting that ATX, LPAR1, and LPAR5 are higher in the immune-high tumor (Cd14-, Cd68-, Cd164-, and Cd3E-high) group, but LPAR2.3 are higher in the immune-low group, suggesting the complex regulatory roles of the ATX–LPA axis in the tumor–immune system interaction." (PMID 31658655, 2019). "During the course of these studies we reported LPAR1 and LPAR3 expression was increased in a subset of human HCC and cirrhotic non-tumor liver (NTL) compared to liver from non-tumor burdened patients." (PMID 26701886, 2016).